AXIN2 (axin 2)
Diseases named in the same sentence as AXIN2 in open-access papers (continued):
Sharing a sentence is not in itself a finding about the gene and the disease.
gastric tumors (1 paper, 2017). "This multicenter study evaluated the association of 9 single nucleotide polymorphisms (SNP) in AXIN2 and CDH1, representing genes consistently altered in breast and gastric tumors, with NSCL ± P in 223 trios (father, mother and patient with NSCL ± P) by transmission disequilibrium test (TDT)." (PMID 28376813, 2017).
GEJ adenocarcinomas (1 paper, 2004). "The AXIN2 gene is an improbable candidate for Wnt activation in GEJ adenocarcinomas because microsatellite instability has been described in only less than 6% in these tumours." (PMID 14970870, 2004).
glaucoma (1 paper, 2023). Increased pressure in the eyeball due to obstruction of the outflow of aqueous humor. "In this study, we identified a causal nexus between the glaucoma-associated gene MYOC and Wnt signaling components AXIN2 and sFRP1 in DEX-treated HTM cells." (PMID 37368816, 2023).
glossitis (1 paper, 2020). Inflammation of the tongue. "A trend for association for association was found between AXIN2 rs11867417 minor allele and the presence of glossitis (p = 7.80E-04, OR = 2.48, 95% C.I. 1.49–4.36)." (PMID 32184411, 2020).
Hepatic fibrosis (1 paper, 2020). The presence of excessive fibrous connective tissue in the liver. "A variety of factors, including PDGF, FGF-2, VEGF, β-catenin, Axin 2, TGF-β1, PAI-1, collagen I, and α-SMA, are key mediators of hepatic fibrosis." (PMID 33178320, 2020).
Hodgkins lymphoma (1 paper, 2021). A heterogeneous group of malignant lymphoid neoplasms of B-cell origin characterized histologically by the presence of Hodgkin and Reed-Sternberg (HRS) cells in the vast majority of cases. "We have recently reported that elevated levels of PRMT5 up‐regulates WNT/β‐CATENIN proliferative signalling through transcriptional repression of pathway antagonists, AXIN2 and WIF1, in three different types of non‐Hodgkin’s lymphoma cells." (PMID 33462997, 2021).
islet cell tumors (1 paper, 2007). "AXIN2 expression was also elevated in islet cell tumors, which likely contributed to its clustering away from the previously identified adenocarcinoma gene clusters." (PMID 17389914, 2007). "Our analysis identified additional genes, including AXL, MFAB, and AXIN2, whose elevated expression in islet cell tumors suggests signal transduction pathways important in their development." (PMID 17389914, 2007).
kidney failure (1 paper, 2019). An acute or chronic condition that is characterized by the inability of the kidneys to adequately filter the blood. "Indeed, Axin2, Cd44, Ccnd1 and to certain extent Myc, showed significantly lower expression in double KO compared with Pkd1 KO mice, both at 10 weeks after DCVC and at kidney failure, suggesting a reduced activation of the canonical Wnt signalling in the absence of Fjx1." (PMID 31038742, 2019).
leiomyoma (1 paper, 2022). A well-circumscribed benign smooth muscle neoplasm characterized by the presence of spindle cells with cigar-shaped nuclei, interlacing fascicles, and a whorled pattern. "Steroid hormone treatment induces nuclear translocation of β‐catenin and their target gene, AXIN2, resulting in the proliferation of leiomyoma stem cells." (PMID 35118811, 2022).
lupus nephritis (1 paper, 2014). Glomerulonephritis in the context of systemic lupus erythematosus. "In this study, we found that the expression of β-catenin and Axin2 in the kidneys of patients with lupus nephritis was increased." (PMID 24465439, 2014).
malnutrition (1 paper, 2023). Inadequate nutrition resulting from poor diet, malabsorption, or abnormal nutrient distribution. "To investigate changes in the distributions of Axin2-CreER+ cells during malnutrition and subsequent catch-up growth, we first developed a mouse catch-up growth model." (PMID 37080994, 2023).
meningioma (1 paper, 2012). A generally slow growing tumor attached to the dura mater. "Regarding downstream gene cascades of Akt, apoptosis-induced genes including CASP9 (3.78-fold), CDKN1A (8.64-fold), AXIN2 (2.78-fold), APC2 (3.12-fold), and EP300 (5.35-fold) were detected with significant down-regulation in fibroblastic meningiomas." (PMID 23285163, 2012).
mesothelioma (1 paper, 2019). A usually malignant and aggressive neoplasm of the mesothelium which is often associated with exposure to asbestos. "In the ceRNA networks, GAS1RR, AXIN2, AC017104.1, RASSF8-AS1, CGN, MIR4458HG, has-miR-125b-5p, LINC01105, and CASP9 were significantly associated with overall survival in mesothelioma." (PMID 31681739, 2019). "AXIN2, CASP9, CGN, RASSF8-AS1, and MIR4458HG were highly expressed in mesothelioma compared to some other types of cancer." (PMID 31681739, 2019). "The integrative analysis of genomics and the clinical profiles using the cBioPortal suggested that AXIN2, CASP9, CGN, RASSF8-AS1, and MIR4458HG were highly expressed in mesothelioma compared to some other types of cancer." (PMID 31681739, 2019). "AXIN2, CASP9, CGN, RASSF8-AS1, and MIR4458HG were expressed in various mesothelioma cell lines but not in immune cells biomarkers." (PMID 31681739, 2019).
multiple myeloma (1 paper, 2014). "Ilimaquinone and ethylsmenoquinone repressed the expression of cyclin D1, c-myc, and axin-2, which are β-catenin/T-cell factor-dependent genes, and inhibited the proliferation of multiple myeloma cells." (PMID 24879546, 2014).
neuroendocrine tumors (1 paper, 2014). "Lately, CpG islands of Axin2 were found methylated in human neuroendocrine tumors (NETs) and Axin2 expression is correspondingly downregulated, which may contributes to the pathogenesis and growth of NETs." (PMID 24474204, 2014).
olfactory neuroblastoma (1 paper, 2020). An olfactory neuroblastoma arising in the paranasal sinus. "As the odds of a chance co-occurrence of a pathogenic AXIN2 variant and an olfactory neuroblastoma are so rare, it is worth exploring potential causation." (PMID 32807118, 2020).
ovarian tumors (1 paper, 2024). "When BRCA2mt ovarian tumors were compared with BRCA1mt tumors, eight genes (NOTUM, SFRP5, RNF43, ZNRF3, DKK1, DKK4, NKD1, and AXIN2) that negatively regulate Wnt signaling were upregulated in BRCA2mt tumors." (PMID 39028933, 2024).
pancreatic adenocarcinoma (1 paper, 2007). "Expression of AXIN2, a marker for Wnt pathway activation, was generally higher in pancreatic adenocarcinomas compared to primary pancreatic duct cells." (PMID 17389914, 2007). "Higher expression of Axin2 in pancreatic adenocarcinomas and islet tumors compared to their non-neoplastic counterparts supports the potential importance of Wnt pathway activation in these tumors." (PMID 17389914, 2007).
Parkinson disease (1 paper, 2022). A progressive degenerative disorder of the central nervous system characterized by loss of dopamine producing neurons in the substantia nigra and the presence of Lewy bodies in the substantia nigra and locus coeruleus. "Axin‐2 knockdown promote mitochondrial biogenesis and dopaminergic neurogenesis by regulating Wnt/β‐catenin signaling in rat model of Parkinson's disease." (PMID 35262262, 2022).
prostate adenocarcinoma (1 paper, 2019). "Taken together, the current study showed evidence that AXIN2 148 C/T and 1365 C/T variants may be associated with decreased cancer susceptibility, especially for lung and prostate adenocarcinoma." (PMID 31080360, 2019). "The overall results indicated that AXIN2 148 C/T variant was associated with cancer risk (allelic contrast: OR = 0.88, 95% CI 0.77–0.99, Pheterogeneity = 0.004; dominant model: OR = 0.82, 95% CI 0.69–0.96, Pheterogeneity = 0.022), especially for lung and prostate adenocarcinoma." (PMID 31080360, 2019).
pulmonary fibrosis (1 paper, 2011). Chronic progressive interstitial lung disorder characterized by the replacement of the lung tissue by connective tissue, leading to progressive dyspnea, respiratory failure, or right heart failure. "We also observed increased expression of the Wnt target gene products MMP-7, cyclin D1, VEGF, and AXIN2 that are thought to play an important role in pulmonary fibrosis." (PMID 21935365, 2011).
renal carcinoma (1 paper, 2025). A carcinoma arising from the epithelium of the renal parenchyma or the renal pelvis. "Next, we found that in renal cancer cells, overexpression of MKRN2 led to elevated β-Catenin phosphorylation and reduced β-Catenin protein expression, resulting in the attenuation of Wnt pathway that is marked by the down-regulation of signature genes (c-Myc, Cyclin D, Axin2, Bcl-2, MMP2, and MMP9)." (PMID 40959281, 2025).
retinoblastoma (1 paper, 2019). A malignant tumor that originates in the nuclear layer of the retina. "A series of canonical pathways, including those involved in Rb (Retinoblastoma)/E2F cell cycle (Rb, E2f2, E2f3, E2f5, Cdk6, DHFR), Notch (Dll1, Notch 2, Jag1), Wnt (Wnt, Axin2, Wisp2/Ccn5) and NF-κB (Ikbip) were found to participate in this network." (PMID 30742662, 2019).
sarcoma (1 paper, 2014). A usually aggressive malignant neoplasm of the soft tissue or bone. "In U2OS cells, SEN461, was shown to modulate the canonical Wnt transcriptional target AXIN2 toghether with CDC25A, recently described as an important mediator of Wnt-induced sarcoma cell proliferation both in vivo and in vitro." (PMID 24842792, 2014).
serous ovarian cancer (1 paper, 2013). "Here we show that recombinant SFRP4 (rSFRP4) treatment of a serous ovarian cancer cell line results in inhibition of β-catenin dependent Wnt signalling as measured by TOP/FOP Wnt reporter assay and decreased transcription of Wnt target genes, Axin2, CyclinD1 and Myc." (PMID 23326605, 2013).
small intestine tumours (1 paper, 2022). "Consistently, in organoids derived from small intestine tumours in ApcMin/+ mice treated with the SETD7 inhibitor (R)-PFI-2 showed reduced initiation of spheres and lower Wnt-dependent gene expression (Lgr5, Axin2 and Lyz1)." (PMID 35326563, 2022).
teratocarcinoma (1 paper, 2008). A germ cell tumor characterized by the presence of an embryonal carcinoma component and a teratoma component. "We focused on a molecule that blocked Wnt-induced reporter activity and also repressed Axin2 expression in 10T1/2 cells and SAX1 and GAD1 expression in teratocarcinoma cells induced with exogenous Wnt3a (data not shown)." (PMID 18698373, 2008).
thymic lymphomas (1 paper, 2012). "To confirm the paradoxical finding that mice lacking Tcf1 suffer from thymic lymphomas due to deregulated high Wnt signaling rather than low, we crossed Tcf1−/− mice with a well-established Wnt-reporter mouse strain, namely the Axin2-LacZ mice." (PMID 23185135, 2012).
thyroid cancer (1 paper, 2017). "Based on this premise, we tested whether exogenous RSPO2 could directly increase β-catenin signaling, using a reporter assay and monitoring AXIN2 expression in control and GPR48/LGR4-knockdown thyroid cancer cells." (PMID 29383135, 2017).
type 1 diabetes (1 paper, 2011). "Our study was designed to assess association of common single nucleotide polymorphisms (SNPs) in four key genes of the canonical Wnt/β-catenin signalling pathway (AXIN2, CTNNB1, LRP5 and LRP6) with DN using a case-control design involving 1467 individuals with type 1 diabetes." (PMID 21876774, 2011).
tumor (238 papers, 2004 to 2026). "BRAF mutations downregulated AXIN2, an important tumor suppressor and regulator of the Wnt/β-catenin signaling pathway in CRC." (PMID 41009348, 2025). "Through this interface, users were able to uncover gender-specific survival trends in AXIN2-mutated cases under microsatellite stability conditions and explore co-mutation enrichment by tumor site." (PMID 40860720, 2025). "Increased Axin2 expression was also associated with tumour-specific H3K27ac enrichment in several regions surrounding the gene." (PMID 37907668, 2023). "Inhibition of tumor proliferation was accompanied by downregulation of Wnt targets such as Axin2 and c-Myc, and loss of cell cycle and stem cell markers." (PMID 35358569, 2022). "Secondly, AXIN2 expression specifically in tumor tissue is positively correlated with transcripts associated with feedback regulation of the Wnt pathway, particularly the Wnt receptor catabolic process." (PMID 32403323, 2020). "Secondly, insufficient original data from the raw articles limited further evaluation of potential interactions, including relationship between the AXIN2 148 C/T, 1365 C/T, and rs4791171 A/G variants and different tumor grade and stage." (PMID 31080360, 2019). "This analysis showed that mutations in AXIN2 found in CRC patients were more frequently in earlier stages of tumor samples derived from the right colon than those derived from the left." (PMID 31632692, 2019). "Comparison of expression levels demonstrated higher levels of both Wif1 and Axin2 within APC2-deficient tumours c,d." (PMID 31291912, 2019). "A nonsense mutation in AXIN1 has been found in one case of EC tumor, while a frameshift mutation in AXIN2 resulting in truncation has been found in another EC tumor." (PMID 31829231, 2019). "Among the Wnt target genes, Axin2 is considered a tumor suppressor and mutations within this gene are associated to cancer development." (PMID 30322153, 2018). "β-catenin downregulation and tumor growth inhibition was associated with reduction in AXIN2, direct transcriptional target of β-catenin, and decreased cancer cell proliferation as measured by Ki67 staining." (PMID 29383099, 2017). "Gain-of-function mutations in the CTNNB1 gene, as well as loss-of-function mutations in the APC and AXIN2 genes, activate the canonical Wnt/β -catenin signaling cascade that regulates self-renewal, survival, proliferation and differentiation of tumor cells." (PMID 29312609, 2017). "Totally 169 published papers were obtained with a combination of search terms as “AXIN2 or axin 2”, “polymorphism or variant or SNP”, and “cancer or tumor or carcinoma”." (PMID 25974148, 2015). "CGK062 repressed the expression of its target genes, including those encoding cyclin D1, c-myc and axin-2, thereby suppressing tumor growth in vitro and in vivo." (PMID 23071615, 2012). "AXIN2 mutations may contribute to abnormal activation of the Wnt signaling pathway and enhance the proliferation and invasion of tumor cells." (PMID 37074454, 2023). "The analysis by NGS of samples from 66 Chinese patients with CCA (44 iCCAs and 22 eCCAs) identified mutations in the AXIN2 gene only in two of these patients (3%), both female, one of each type of tumor, and alterations were associated with tumor mutational burden." (PMID 37190050, 2023).
tumor (continued). "Strikingly, they found that ligand-dependent tumours tend to silence genes encoding Wnt antagonists, such as AXIN2, NKD1, APCDD1, NOTUM, and DKK4, whereas ligand-independent tumours effectively bypass Wnt-pathway negative feedback loops without the need for such selective pressure." (PMID 33673710, 2021). "More interestingly, germline mutations of AXIN2 had a high tumor mutation burden in our results." (PMID 31769227, 2020). "The AXIN2-correlated transcriptome in tumor tissue trumps however, in its association with transcripts indicating regulation of Wnt signaling, particularly Wnt receptor catabolic processes, and contrasting with all LEF/TCF-correlated transcriptomes, apart from, interestingly, that of TCF7." (PMID 32403323, 2020). "Moreover, in the tissue sections, the area of the tumour-associated stroma was predominantly increased at the tumour-bone interface in CA9–22Mock or HSC-2Mock cell-bearing mice compared to the related Axin2-knockdown cell-bearing mice (C, i-ii)." (PMID 33046030, 2020). "Also, there was an association with the tumor location, being AXIN2 gene more frequently mutated in tumor samples derived from the right colon than those derived from the left." (PMID 31632692, 2019). "We identified three tumour suppressor genes associated with Wnt signalling, namely, AXIN2, DKK3 and SFRP1, that could potentially be suppressed by miR-582-3p." (PMID 26468775, 2015). "Subsequently, it binds to transcription factors and drives the uncontrolled expression of target genes implicated in cell proliferation, transformation, and tumor progression, such as Myc, matrix metalloproteinase 7, Axin-2, the cell adhesion molecule L1-CAM, the metastasis gene S100A4, and others." (PMID 22640921, 2012). "Finally, the knockdown of Axin2 or β-catenin could reverse the tumor-promoting effects caused by CUX1 overexpression, suggesting that CUX1 induced gliomagenesis and malignant phenotype by activating the Wnt/β-catenin signaling pathway." (PMID 34422906, 2021). "An interesting exception to this rule is the stronger association between TCF7 and AXIN2 expression in tumor tissue, which could suggest some specificity in TCF7-mediated WNT/β-catenin signaling in human tumor tissue, supporting earlier such suggestions in the mouse model." (PMID 32403323, 2020). "AXIN2 downregulation leads to a dysregulated Wnt/β-catenin pathway whose over activation leads to aberrant cell proliferation and tumor growth in CRC." (PMID 41009348, 2025). "SOX4, LGR5, AXIN2, cMYC, and this signature, together with tumor cell proliferation, are abrogated in vitro by the inhibition of TCF function through dominant-negative TCF (dnTCF4) expression." (PMID 41303422, 2025). "This analysis showed that a subset of AXIN2 positive/SALL2-positive cells in the tumor organoids microenvironment depicts a strong positive correlation between the two genes." (PMID 40869218, 2025). "Downstream of β-catenin, target genes such as TCF1, Cyclin D1, Axin2, Lgr5, and c-Myc promote cell cycle progression in both tumor cells and SSCs." (PMID 40638605, 2025). "Downregulation of TCF signaling by dominant negative TCF4 (dnTCF4) led to reduced expression of TCF targets, including c-Myc, BMP-4, Axin-2, and Lef-1, in all three tumors, as well as inhibition of tumor cell proliferation in AGS." (PMID 41303422, 2025). "Out of the 94 patients, skin biopsies of 52 patients and 35 paired tumor biopsies showed reduction in axis inhibition protein 2 (AXIN2), which confirmed the inhibition of the Wnt pathway." (PMID 40869407, 2025). "To assess the relative activation of the WNT signaling pathway among the different tumor groups, we measured expression levels of Axin2, a well-established WNT downstream target." (PMID 38902475, 2024).